TCN1 (transcobalamin 1)
Diseases named in the same sentence as TCN1 in open-access papers (continued):
Sharing a sentence is not in itself a finding about the gene and the disease.
Pancreatic Cancer (2 papers, 2020 to 2025). "We found that the protein transcobalamin 1 (TCN1) is markedly increased in pancreatic tumors and is linked to worse clinicopathologic features and poorer survival." (PMID 41154358, 2025). "Collectively, these findings indicate that TCN1 promotes pancreatic cancer malignancy by activating DUOX2-dependent signaling, which drives ROS generation and facilitates aggressive tumor behavior." (PMID 41154358, 2025). "To further elucidate the biological significance of TCN1 in pancreatic cancer progression, we selected BxPC-3 (high TCN1 expression) and PANC-1 (low TCN1 expression) cell lines based on their differential gene expression profiles." (PMID 41154358, 2025). "Functional characterization revealed that TCN1 enhances pancreatic cancer cell proliferation, migration, invasion, and epithelial–mesenchymal transition (EMT) in both in vitro and in vivo models, thereby accelerating tumor progression." (PMID 41154358, 2025). "Functional investigations showed that TCN1 enhanced pancreatic cancer cell proliferation, migration, invasion, and epithelial–mesenchymal transition (EMT) in both in vitro and in vivo models." (PMID 41154358, 2025). "Analysis of pancreatic cancer tissues from the GEPIA database revealed a strong positive correlation between TCN1 and DUOX2 expression, further supporting their regulatory relationship." (PMID 41154358, 2025). "EdU proliferation and colony formation assays revealed that TCN1 knockdown significantly suppressed pancreatic cancer cell proliferation, whereas STAT4 overexpression rescued this inhibitory effect." (PMID 41154358, 2025). "Functional assays further showed that TCN1 drives malignant phenotypes in pancreatic cancer by promoting proliferation, migration, and EMT, a pivotal process enabling tumor invasion and metastasis." (PMID 41154358, 2025). "To further delineate the mechanism through which the TCN1/STAT4/DUOX2 axis promotes pancreatic cancer malignancy, we systematically performed functional rescue experiments in BxPC-3 and PANC-1 cells." (PMID 41154358, 2025). "Collectively, these findings indicate that TCN1 acts as a key regulatory molecule in pancreatic cancer, sustaining tumor growth by promoting proliferative activity." (PMID 41154358, 2025). "Furthermore, to investigate the role of TCN1 in pancreatic cancer progression, we established stable TCN1-knockdown (BxPC-3) and TCN1-overexpressing (PANC-1) cell lines through lentiviral infection, with successful modulation confirmed using qRT-PCR." (PMID 41154358, 2025). "However, whether TCN1 drives pancreatic cancer progression through DUOX2-dependent signaling remains unverified." (PMID 41154358, 2025). "In a previous study, we established the functional roles of TCN1 and DUOX2 in pancreatic cancer progression and their regulatory relationships." (PMID 41154358, 2025). "There were three proteins (COL10A1, DKK1, and TCN1) with no information in HPA; thus, it is not possible to report about the protein expression in pancreatic cancer." (PMID 32005189, 2020).
ulcerative colitis (2 papers, 2025). An inflammatory bowel disease involving the mucosal surface of the large intestine and rectum. "In inflammatory conditions like ulcerative colitis, TCN1 expression can be altered by inflammation." (PMID 41221285, 2025).
acne (1 paper, 2021). An inflammatory process of the sebaceous glands which is characterized by comedones, nodules, papules and/or pustules on the skin. "It was demonstrated by microarray and experimental methods that TCN1 and S100A12 may affect the disease process of acne by participating in the innate immune and cellular differentiation processes of hair follicles and epidermal keratin-forming cells." (PMID 35047008, 2021).
actinic keratosis (1 paper, 2023). A precancerous lesion of the skin composed of atypical keratinocytes. "Five new genes, HEPHL1, FBN2, SULF1, SULF2, and TCN1, were recently discovered in cSCC, which were significantly upregulated compared to normal skin (p < 0.001) and actinic keratosis (AK) (p < 0.01)." (PMID 36980718, 2023).
adenomyosis (1 paper, 2020). The growth of endometrial tissue inside the muscular wall of the uterine corpus. "SPP1, LIF, TCN1 and CLDN4 were common to adenomyosis and healthy groups of genes, while ANXA2, EDNR8, MMP26, DEPP1, ABCC3, CDA and SLC1A1 were common to endometriosis and healthy groups." (PMID 32933042, 2020).
Allergy (1 paper, 2024). An allergy is an immune response or reaction to substances that are usually not harmful. "Four allergy patients carry the heterozygous (AG) genotype in the TCN1 genetic variant, four have the heterozygous (AG) genotype, and three allergy patients have the homozygous (GG) genotype in the MTRR polymorphism." (PMID 38807972, 2024).
autism (1 paper, 2024). Persistent deficits in social interaction and communication and interaction as well as a markedly restricted repertoire of activity and interest as well as repetitive patterns of behavior. "Three autism patients are heterozygous in the Transcobalamin (TCN1) (rs526934-G) gene, six are heterozygous in the methionine synthase reductase (MTRR) (rs1801394-G) gene, and one is homozygous (GG) in the MTRR gene." (PMID 38807972, 2024). "In our study, three of the autism patients were heterozygous (AG) in the TCN1 (rs526934) gene, six were heterozygous (AG) in the MTRR (rs1801394) gene, and one was a homozygous (GG) genotype in the MTRR gene." (PMID 38807972, 2024).
autism spectrum disorder (1 paper, 2024). A spectrum of developmental disorders that includes autism, and Asperger syndrome. "ASD: Autism Spectrum Disorder; AT: Autoimmune Thyroiditis; MTHFR: Methylenetetrahydrafolatreductase; TCN1: Transcobalamin 1; TCN2: Transcobalamin 2; MTRR: Methionine synthase reductase; PEMT: Phosphoethanolamine N-Methyltransferase." (PMID 38807972, 2024).
autoimmune disease (1 paper, 2025). A disorder resulting from loss of function or tissue destruction of an organ or multiple organs, arising from humoral or cellular immune responses of the individual to their own tissue constituents. "Furthermore, TCN1 is implicated in autoimmune diseases, where it may help regulate inflammatory responses." (PMID 41221285, 2025).
cholera (1 paper, 2011). "Such regulation of TCN1 is supported by a report showing induction of TCN1 RNA in the intestinal epithelium of cholera patients compared to healthy controls." (PMID 22174891, 2011).
Cognitive impairment (1 paper, 2018). Abnormal cognition is characterized by deficits in thinking, reasoning, or remembering. "Our results suggest that transcriptional dysregulation of TCN1 may be a contributing factor to the cognitive impairments associated with severe mental disorders." (PMID 30139959, 2018). "Furthermore, the expression pattern of TCN1 across diagnostic categories suggests that the cognitive impairments associated with SCH and BD may partly be attributed to changes in TCN1 expression levels." (PMID 30139959, 2018).
Impaired glucose tolerance (1 paper, 2012). An abnormal resistance to glucose, i.e., a reduction in the ability to maintain glucose levels in the blood stream within normal limits following oral or intravenous administration of glucose. "TCN1 (Chr 1, LOD = 4.41) has shown linkage to serum insulin concentrations in impaired glucose tolerance." (PMID 22957057, 2012).
liver disorder (1 paper, 2022). A disease involving the liver. "Concentrations of TCN1 have been shown to be elevated in the plasma of patients with several liver disorders, including cancer." (PMID 36364737, 2022).
myeloid leukemia (1 paper, 2022). A clonal proliferation of myeloid cells and their precursors in the bone marrow, peripheral blood, and spleen. "Furthermore, it has been well established that high serum levels of vitamin B12 are associated with malignant hematological diseases such as chronic acute leukemia and myeloid leukemia, which are caused by granulocyte proliferation releasing TCN1." (PMID 35287670, 2022).
rheumatoid arthritis (1 paper, 2012). A chronic, systemic autoimmune disorder characterized by inflammation in the synovial membranes and articular surfaces. "TCN1 protein was also increased in synovium of rheumatoid arthritis, and was significantly associated with cholesterol levels or statin response, perhaps providing a predisposing link between both skin inflammation and high cholesterol." (PMID 22957057, 2012).
tumor (20 papers, 2014 to 2026). "Transcobalamin (TCN1) is a vitamin B12-binding protein usually highly expressed in tumor tissues and linked to aggressive tumor behavior and poor prognosis." (PMID 35729678, 2022). "In this study, we analyzed TCN1 differential expression, diagnostic value, and prognostic value, and we also analyzed the association with tumor immune infiltration in LUAD." (PMID 35287670, 2022). "Recent studies and bioinformatic analyses have found that TCN1 is highly expressed in cancer tissues and is associated with tumour aggressiveness and poor prognosis." (PMID 32686693, 2020). "DUOX2 restoration fully reversed the tumor volume reduction caused by TCN1 knockdown." (PMID 41154358, 2025). "The overexpression of TCN1 in tumor tissues causes tumorigenesis and poor biological behavior." (PMID 35287670, 2022). "NDRG1 contributes to tumor aggressiveness by cell proliferation and lipid metabolism regulation, whereas GAPVD1, INPP5A, TCN1, SAV1, RBBP8, SPIB, and UBE2A also exhibit oncogenic or tumor-suppressive properties associated with prognosis." (PMID 41511940, 2026). "To directly evaluate the impact of TCN1 on tumor cell metastasis in vivo, we established a nude mouse hepatic metastasis model." (PMID 41154358, 2025). "Conversely, co-knockdown of DUOX2 in TCN1-overexpressing tumors significantly suppressed TCN1-driven tumor growth." (PMID 41154358, 2025). "Conversely, TCN1-overexpressing orthotopic tumors displayed accelerated growth and significantly increased tumor mass and volume." (PMID 41154358, 2025). "IHC of orthotopic tumor tissues from nude mice corroborated these findings: TCN1-knockdown tumors exhibited reduced N-cadherin and vimentin expression, but increased E-cadherin expression." (PMID 41154358, 2025). "Collectively, these findings establish TCN1 as a consistently overexpressed molecular feature in PDAC, with its expression levels strongly associated with tumor stage, histological differentiation, and patient survival." (PMID 41154358, 2025). "In cell and mouse models, raising TCN1 enhanced tumor cell growth, movement, and invasion, while lowering TCN1 reduced these behaviors." (PMID 41154358, 2025). "Increased TCN1 expression promoted the xenograft growth of tumor cells, and TCN1 inhibition delayed the xenograft growth of tumor cells." (PMID 35716043, 2023). "The results demonstrated that DIRAS3, IZUMO4, and TCN1 had a lower expression in tumor cells than in normal breast epithelial cells." (PMID 36685928, 2022). "The GSVA package of R was used to observe the tumor-infiltrating immune cell levels in relation to TCN1 expression in order to explore its possible role in the immune system." (PMID 35287670, 2022). "High TCI and TCII levels are observed in tumor samples, which argues for an intratumoral synthesis of transcobalamins, supported by the overexpression of TCN1 and TCN2 in cancers cells." (PMID 35631199, 2022). "In tumor tissues, TCN1 is expressed highly, and its expression is correlated with cancer aggressiveness and poor prognosis according to recent studies and bioinformatic analyses." (PMID 35287670, 2022). "First, we examined the expression of TCN1 in various tumor and normal tissue types using the TCGA database and GTEx database." (PMID 35287670, 2022). "Research suggested that TCN1 is negatively related to patient’s prognosis, and it can promote tumor migration, invasion, and reduce the chemotherapy sensitivity of cancer cells." (PMID 33968130, 2021). "Based on the COAD cohort in the GEPIA database, further bioinformatics analyses were performed and confirmed that TCN1 was significantly upregulated in CRC tissues (n = 275) compared with non-tumour tissues (n = 349) (P < 0.05)." (PMID 32686693, 2020). "After treatment with platinum-containing neoadjuvant chemotherapy, TCN1 expression in tumour tissues was decreased(P = 0.009)." (PMID 32686693, 2020).
tumor (continued). "Furthermore, the antioxidant N-acetylcysteine (NAC) and 4-Hydroxy-TEMPO (Tempol) effectively reversed TCN1-driven tumor progression, further supporting ROS as the critical effector molecule within this signaling axis." (PMID 41154358, 2025). "Furthermore, our study examined the relationship between TCN1 mRNA levels and tumor-infiltrating immune cells." (PMID 35287670, 2022). "TCN1 gene expression is upregulated in tumor cells, which could be related to cellular events that are typical to cancer, such as apoptosis and inflammation." (PMID 36364737, 2022). "This stemness-associated signature integrates developmental drivers such as PTPRH, AHNAK2, PCDH7, metabolic regulators CPS1, SFTPB, and hypoxia-responsive factors such as TCN1, TMPRSS11E, reflecting the multifaceted nature of OSA-induced tumor evolution." (PMID 41584048, 2026). "Taken together, we confirmed that increased TCN1 enhanced VB12 transport and promoted tumor growth through the inhibition of cell apoptosis." (PMID 35716043, 2023). "From the GEPIA, we found the low TCN1 expression level in normal BD, suggesting that TCN1 overexpression enhanced VB12 absorption in CCAs, thus promoting tumor growth." (PMID 35716043, 2023). "Gelatinase activity was one major GO annotation of these eight genes (CA7, SPIB, GUCA2B, AQP8, IL6R, SPP1, TCN1, and CWH4) and is related to tumor progress and metastasis." (PMID 24959000, 2014). "Collectively, the data point to a functional connection among TCN1, STAT4, and the DUOX2/ROS axis that, by modulating oxidative stress, may constitute a tumor cell–autonomous oncogenic route in PDAC." (PMID 41154358, 2025). "IHC of tumor tissues mirrored these results, showing reduced DUOX2 staining in TCN1-knockdown tumors and elevated staining in TCN1-overexpressing tumors, indicating the transcriptional and translational regulation of DUOX2 by TCN1." (PMID 41154358, 2025). "Conversely, TCN1 overexpression upregulated DUOX2 expression and promoted EMT, and this effect was abolished by STAT4 knockdown, indicating that TCN1 regulates DUOX2 through STAT4 to drive EMT-mediated tumor aggressiveness." (PMID 41154358, 2025). "Although traditional studies have focused on the involvement of TCN1 in tumorigenesis through these canonical metabolic pathways, its non-canonical mechanisms within the tumor microenvironment remain unclear." (PMID 41154358, 2025). "Methods and Results: Through integrated analysis of TCGA and GTEx datasets combined with 80 clinical specimens, we identified significant TCN1 overexpression in PDAC, showing a positive association with tumor stage and negative associations with histological differentiation and overall survival." (PMID 41154358, 2025).
cancer (14 papers, 2014 to 2025). A tumor composed of atypical neoplastic, often pleomorphic cells that invade other tissues. "High expression of TCN1, a vitamin B12-binding protein, is positively associated with cancer aggressiveness and a poor prognosis." (PMID 37920207, 2023). "For instance, if the genetic variants that are associated with B12 are also associated with TCN1, and if TCN1 is associated with cancer, then there is an alternative causal path between the genotype and cancer, other than that via vitamin B12." (PMID 36364737, 2022). "Numerous polymorphisms in genes related to vitamin B12 metabolism or transport have been studied in relation to cancer risk (i.e., rs526934 in the TCN1 gene, and cubulin haplotypes)." (PMID 36364737, 2022). "In different cancer types, TCN1 expression has been associated with TILs." (PMID 35287670, 2022). "Larger and more aggressive tumors appear to produce more TCN1 that could be, in theory, released to the blood and become available to capture vitamin B12, and cause high B12 in people with cancer." (PMID 36364737, 2022). "As expected, the result proved that TCN1 is associated with many cancer-related genes and pathways, which provided evidence that TCN1 might affect tumourigenesis and progress by affecting transcription." (PMID 32686693, 2020). "Indeed, a prospective assessment of the association between the overexpression of TCN1/TCN2/CD320 or high loads of TCI/TCII/TCII-R on immunohistological analyses of cancer tissues and their resistance to treatment, or for the prognosis, will help to adapt the treatment and survey strategy." (PMID 35631199, 2022). "The results revealed that the cancer cell subclusters c8_TOP2A, c9_HMGB2, c12_MKI67, and c13_TK1 were dominantly in a cycling state, while c1_TCN1, c2_CD74, c3_CD24, c5_CEACAM6, and c10_SAT1 were mainly in a quiescent state." (PMID 36529697, 2023). "As little research has been done on cancer and the TCN1 gene, we decided to perform an advanced bioinformatic analysis to investigate its potential regulatory mechanisms and biological functions in LUAD." (PMID 35287670, 2022). "TCN1 is a regulator of the Wnt/beta-catenin pathway and enhances the expression of the target genes of beta-catenin, leading to cancer progression and outcome deterioration." (PMID 24959000, 2014). "Our findings are in accordance with previous research regarding the TCN1 role in other cancers." (PMID 35287670, 2022). "The excessive release of TCN1 from cancer tissues could lead to capturing B12 and trapping it in the circulation, instead of storing the vitamin in the tissues." (PMID 36364737, 2022). "A higher serum level of TCN1 and vitamin B12 has been reported in cancer patients." (PMID 35287670, 2022). "Therefore, inhibiting the expression of TCN1 might increase cancer cell apoptosis and restrain its proliferation, thus making it a promising therapy in CCA." (PMID 35716043, 2023). "A similar plasma B12/holoTC ratio in patients with cancer and the controls suggests that the proportion of B12 bound to TCN1 to that bound to transcobalamin is unchanged in patients with cancer, thus both B12-binding proteins may be upregulated to the same extent." (PMID 36364737, 2022). "Regarding the molecular mechanisms, future studies may detect neutrophil enrichment in tumors and the co-localization of TCN1 with other structural or functional proteins or proliferative markers, to explain the role of TCN1 in cancer development (cancer progression or arrest)." (PMID 36364737, 2022). "TCN1 may have a role in cancer progression or in the response of the body against cancer." (PMID 36364737, 2022). "In addition, genetic factors could lead to the high expression of TCN1 in cancer tissues, which may in theory trap more vitamin B12 in plasma." (PMID 36364737, 2022). "TK1, TCN1, CAV1, and HS3ST2 play indispensable roles in survival predictions and pathogenesis of various cancers." (PMID 35898471, 2022).
cancer (continued). "High expression of TCN1 and UPP1 was present in many malignant cancers." (PMID 35073659, 2024). "An open question is whether vitamin B12 binders (TCN1 and TCN2) are upregulated to the same degree in patients with cancer." (PMID 36364737, 2022). "The relative mRNA expression level of TCN1 in cancer tissues was higher than in non-cancerous tissues (0.601 ± 0.024 vs. 0.335 ± 0.018, P < 0.001)." (PMID 32686693, 2020).
psychiatric disease (1 paper, 2018). "The effect size of TCN1 expression on memory performance is comparable to that of age, sex, and mental illness, all of which are known determinants of memory function." (PMID 30139959, 2018).